RPP14 (ribonuclease P/MRP subunit p14)
Description:
Component of ribonuclease P, a ribonucleoprotein complex that generates mature tRNA molecules by cleaving their 5'-ends.
Synonyms: P14
Tractability: PROTAC: its protein half-life has been measured.
Gene: Protein-coding gene on chromosome 3 (58,306,245 to 58,324,695, forward strand). Ensembl gene ENSG00000163684.
Subcellular location: Nucleus, nucleolus
Subcellular location (Human Protein Atlas): Cytosol; Nucleoplasm
Pathways (Reactome):
Metabolism of RNA: Major pathway of rRNA processing in the nucleolus and cytosol; tRNA processing in the nucleus
Gene Ontology:
Molecular function: protein binding; ribonuclease P activity; ribonuclease P RNA binding
Biological process: tRNA 5'-leader removal; RNA processing; tRNA processing
Cellular component: multimeric ribonuclease P complex; nucleolar ribonuclease P complex; nucleolus; ribonuclease MRP complex; nucleoplasm; nucleus; endoribonuclease complex; ribonuclease P complex; ribonucleoprotein complex
Genetic constraint (gnomAD): Loss-of-function variants: 17 observed, 16.18 expected, observed/expected ratio (o/e) 1.05, 90% interval 0.72 to 1.57. The upper end of that interval is the gene's LOEUF score, 1.57, which puts it in group 6 of 6, group 1 being the genes least tolerant of losing a copy. Missense variants: 111 observed, 125.73 expected, observed/expected ratio (o/e) 0.88, 90% interval 0.76 to 1.03. Synonymous variants: 49 observed, 49.85 expected, observed/expected ratio (o/e) 0.98, 90% interval 0.78 to 1.25.
Homologues: Orthologues: chimpanzee RPP14 (100% identical), guinea pig RPP14 (91% identical), mouse Rpp14 (84% identical), rabbit RPP14 (75% identical), tropical clawed frog rpp14 (65% identical), zebrafish rpp14 (58% identical), Drosophila melanogaster Rpp14a (21% identical), Drosophila melanogaster Rpp14b (17% identical).
Diseases named in the same sentence as RPP14 in open-access papers:
RPP14 is named in the same sentence as 2 diseases in open-access papers, as found by Europe PMC text mining. Sharing a sentence is not in itself a finding about the gene and the disease. The quoted sentences say what the papers report.
breast carcinoma (1 paper, 2022). "No previous report was found on the impact of RPP14 in bone metabolism or breast cancer." (PMID 35685372, 2022). "GDF11, CD151, PAFAH1B2 and YTHDF2 may play a pivotal role in the predisposition of metastasis to the bone from breast cancer, whilst DPP9, FAS, ZNF519, RPP14 and FAU may be actively involved in the adaptative colonisation of metastatic breast cancer cells in bone." (PMID 35685372, 2022).
RPP14 also shares sentences with these, for which no sentence is quoted: COVID-19 (1 paper).